NLRP3 (NLR family pyrin domain containing 3)
Diseases named in the same sentence as NLRP3 in open-access papers (continued):
Sharing a sentence is not in itself a finding about the gene and the disease.
atherosclerosis (continued). "IL-1β and IL-18 are two key in?ammatory factors in atherosclerosis development and are mainly regulated by the NLRP3 inflammasome." (PMID 34094640, 2021). "This review not only summarizes the role of the NLRP3 inflammasome in atherosclerosis but also discusses its role in CAD and myocardial I/R injury after an acute MI, thereby providing an in depth overview of its dual role in coronary artery disease." (PMID 32648087, 2021). "The role of NLRP3 inflammasome in cardiovascular disease has been reported and confirmed to be involved in hyperhomocysteinemia (HHcy)-aggravated inflammation and atherosclerosis." (PMID 34299310, 2021). "Mouse studies were used to investigate the effects of the NLRP3 inflammasome’s downstream cytokines, IL-1β, and IL-18 on atherosclerosis in the early 2000s." (PMID 32648087, 2021). "NLRP3 inflammasome is a vital player in macrophages pyroptosis, which is a type of proinflammatory cell-death and takes part in the pathogenesis of atherosclerosis." (PMID 34588488, 2021). "The NLRP3 inflammasome is an innate immune signaling complex that has been shown to be a key mediator in the production of IL-1 cytokines in atherosclerosis." (PMID 34522180, 2021). "The NLRP3 inflammasome is positively correlated with the severity and prognosis of atherosclerosis in patients with acute coronary syndrome." (PMID 35096837, 2021). "Impaired CMA has also been proven to increase NLRP3 inflammasome activation and secretion of IL-1β, promoting vascular inflammation and atherosclerosis." (PMID 35096837, 2021). "Current research on the effect of SGLT2i on NLRP3 inflammasome is focused on diabetic nephropathy, steatohepatitis, cardiomyopathy and atherosclerosis." (PMID 33754074, 2021). "With the continuous deepening of study, the mechanism of NLRP3-mediated ECs pyroptosis in the initiation of atherosclerosis has been gradually discovered." (PMID 34122076, 2021). "Important functional molecules that result in pyroptosis, including NLRP3, AIM2, and caspase-1, are abundantly expressed and activated in atherosclerosis and are associated with the occurrence, accumulation, and destabilization of atherosclerotic plaques." (PMID 35096837, 2021). "Observations: Cholesterol promotes the development of atherosclerosis by activating NLR family pyrin domain containing 3 (NLRP3), and the resulting inflammatory environment indirectly contributes to COVID-19 infection and subsequent deterioration." (PMID 34522180, 2021). "As a macromolecular complex, the NLRP3 inflammasome has been reported to be involved in many CVDs, including atherosclerosis, ischemia/reperfusion (I/R) injury, and HF." (PMID 34257682, 2021). "In a mouse model of atherosclerosis, the inhibition of the NLRP3 inflammasome by MCC950 resulted in a significant reduction in atherosclerotic lesions." (PMID 34885795, 2021). "In this study, we used apoE−/− mice and ox-LDL induced THP-1 derived macrophages to explore the mechanisms of MCC950, a selective NLRP3 inhibitor in treating atherosclerosis." (PMID 34588488, 2021). "The inflammatory responses in atherosclerosis are mainly developed through the NLRP3 inflammasome, interleukin‐1 beta (IL‐1β) and interleukin‐6 (IL‐6) inflammatory response axis and eventually lead to an increase in the C‐reactive protein (CRP)." (PMID 34312998, 2021). "All of these data demonstrate the critical role of the NLRP3 inflammasome in the pathogenesis of cardiovascular disease, especially atherosclerosis." (PMID 32378144, 2021). "In the last 2 decades, multiple studies unveiled evidence that the NLRP3 inflammasome has a role in the pathogenesis of atherosclerosis, coronary artery disease, and myocardial ischemia reperfusion injury." (PMID 32648087, 2021). "Nicotine, a major preventable risk factor for atherosclerosis, can lead to VEC pyroptosis and subsequently secretes inflammatory cytokines by ROS/NLRP3/caspase‐1 pathway." (PMID 34590363, 2021).
atherosclerosis (continued). "The role of inflammation and the NLRP3 inflammasome in atherosclerosis has been studied extensively in atherosclerotic mouse models." (PMID 32648087, 2021). "NLRP3 inflammasome is upregulated after several cardiovascular diseases such as atherosclerosis, myocardial infarction, hypertension, chronic heart failure, ischemic heart disease, and diabetic cardiomyopathy." (PMID 34439517, 2021). "Intracellular ROS participate in NLRP3 inflammasome activation in HHcy mice model and the high-fat diet (HFD)-induced atherosclerosis model using apolipoprotein E deficient (ApoE−/−) mice." (PMID 34299310, 2021). "At present, the inflammatory bodies most closely related to atherosclerosis are mainly NLRP3 inflammatory bodies which are members of the NLR family." (PMID 35087837, 2021). "The pathogenesis of many inflammatory disorders, including atherosclerosis, gout, Crohn’s disease, and periodontitis has been related to the inflammasomes NLRP3 and IL-1." (PMID 34501201, 2021). "Nowadays, the NLRP3 inflammasome, a main generator of activated IL-1 family cytokines, is extensively studied due to its crucial role in the pathogenesis of atherosclerosis." (PMID 33807807, 2021). "In atherosclerosis, OxLDL can directly activate the downstream NF‐κB signal transduction pathway through DAMP to increase the NLRP3 inflammasome of the expression, ASC (apoptosis‐associated speck‐like protein containing a CARD), pro‐IL‐1 β and pro‐IL‐18." (PMID 34312998, 2021). "It is well-known that the deregulated NLRP3 inflammasome drives the progression of many inflammatory, metabolic, degenerative and aging-related diseases, such as atherosclerosis, gout, type 2 diabetes, autoimmune disorders, and Alzheimer’s disease." (PMID 33976226, 2021). "Mitochondrial dysfunction in connection with NLRP3 inflammasome activation has been reported to play a role in inflammatory diseases such as diabetes, atherosclerosis, neurological disorders, cardiovascular disease, and kidney disease." (PMID 33670601, 2021). "The study of bone marrow-derived mesenchymal stem cells microvesicles (BMSCs-MVs) on the treatment of atherosclerosis in mice showed that miR-223 inhibited macrophages pyroptosis by reducing the expression of NLRP3." (PMID 34122076, 2021). "As the most representative pyroptosis-related inflammasome in response to a variety of membrane damage signals, NLRP3 is involved in the pathological process of numerous inflammation-related diseases such as cancer, atherosclerosis, diabetes, and obesity." (PMID 34122076, 2021). "Mechanisms of NLRP3/IL-1β regulation and involvement of the pathway in atherosclerosis pathogenesis were covered in recent reviews." (PMID 34440119, 2021). "Lipid raft destructor MβCD inhibits nicotine-induced NLRP3 inflammasome activation in macrophage and alleviates nicotine-accelerated atherosclerosis." (PMID 34490270, 2021). "The NLRP3 inflammasome plays an essential role in the pathogenesis of various cardiovascular diseases such as hypertension, atherosclerosis, and myocardial infarction." (PMID 34439517, 2021). "NLRP3 present in the cytoplasmic matrix of macrophages and foam cells can initiate atherosclerosis when cholesterol crystals are engulfed by macrophages via their CD36 receptors, resulting in activation of the NLRP3 inflammasome via lysosomal damage." (PMID 33923537, 2021). "Human atherosclerotic lesions show increased expression of the major components of NLRP3, and inhibition of the NLRP3 inflammasome reduces atherosclerosis in Apoe-−/− and ApoE2-Ki mice." (PMID 35008500, 2021). "NLRP3 inflammasomes are strongly expressed in the aortas of patients with coronary atherosclerosis, and NLRP3 ablation mitigates the development of atherosclerosis in mice." (PMID 34094640, 2021). "This review summarizes the role of the NLRP3 inflammasome in atherosclerosis, CAD, and myocardial I/R injury." (PMID 32648087, 2021).
atherosclerosis (continued). "Previous research has shown that ox-LDL and extracellular acidosis exacerbate atherosclerosis by activating the NLRP3 inflammasome." (PMID 33626512, 2021). "It has previously been known that TXNIP/NLRP3 inflammasome is activated by ER stress in several diseases, sunch as diabetes mellitus, some neurodegenerative diseases and atherosclerosis, however, related data is scarce in ischemic retinopathy." (PMID 33933165, 2021). "The current study demonstrated that nicotine activated NLRP3 inflammasome in macrophage and accelerated atherosclerosis by inducing the accumulation of α1-nAChR in lipid raft." (PMID 34490270, 2021). "More recently, in two mouse models of atherosclerosis, Tranilast promoted NLRP3 ubiquitination, limiting NLRP3 inflammasome assembly and thus resulting in a blunted initiation and progression of atherosclerotic plaques." (PMID 33673188, 2021). "In atherosclerosis, colchicine can inhibit the assembly and activation of NLRP3 inflammasome via various mechanisms to effectively reduce the expression of inflammatory factors, thereby reducing the inflammation." (PMID 34312998, 2021). "Various signs indicate that ROS/NF-κB/NLRP3 axis plays an important role in ECs pyroptosis in the initiation of atherosclerosis." (PMID 34122076, 2021). "OxLDL has been shown both to prime and to activate the NLRP3 inflammasome in macrophages in mouse models of atherosclerosis." (PMID 35008500, 2021). "What is more, MβCD inhibited nicotine-triggered NLRP3 inflammasome activation and reduced nicotine-induced macrophage recruitment to atherosclerotic plaque, thus preventing the progression of atherosclerosis in the aorta of apoE–/– mice fed with high-fat diet." (PMID 34490270, 2021). "Berberine, an active component of coptis chinensis, can inhibit the activation of ROS-dependent NLRP3 inflammatory bodies and reduce the synthesis of pro-IL-1β by inhibiting NF-κB, so it can be used in the prevention and treatment of atherosclerosis." (PMID 35087837, 2021). "The activation of NLRP3 inflammasome and the subsequent release of IL-1β and IL-18 contribute to the pathogenesis of atherosclerosis and HF 141-143." (PMID 33754074, 2021). "In contrast, numerous studies have manifested the relevant significance of the NLRP3 inflammasome in atherosclerosis." (PMID 33807807, 2021). "Next to CCs and oxLDL, calcium phosphate crystals also contribute to the progression of atherosclerosis and the instability of plaques through activation of the NLRP3 inflammasome." (PMID 32648087, 2021). "Cytokine storm involved in heart failure, myocardial fibrosis, atherosclerosis and cardiotoxicity induced by anticancer drugs is induced by overexpression of MyD88 and NLRP3 inflammasome." (PMID 34178667, 2021). "MiR-30c-5p downregulates FOXO3 expression, inhibiting NLRP3-mediated EC pyroptosis in atherosclerosis." (PMID 35004893, 2021). "In this study, we created a new model of VSMCs specifically expressing sterol-resistant SCAP (D443N mutant) in both C57BL/6J and ApoE-/- mice to reveal the effects of SCAP on the NLRP3 inflammasome in VSMCs and the development of atherosclerosis." (PMID 34094640, 2021). "Monosodium glutamate is another DAMP signal for activation of NLRP3 and initiation of several inflammatory events, including atherosclerosis." (PMID 33923537, 2021). "The inflammatory responses in atherosclerosis are mainly mediated by the NLRP3 inflammasome and its downstream inflammatory factors." (PMID 34312998, 2021). "Accumulating evidence has demonstrated that NLRP3 inflammasome-regulated inflammatory responses are responsible for the development of atherosclerosis." (PMID 34414181, 2021). "Recently, it was shown that excessive activation of NLRP3 represented a pivotal mechanism in the pathogenesis of metabolic diseases such as type 2 diabetes, obesity, gout, and atherosclerosis." (PMID 32378144, 2021).
atherosclerosis (continued). "The NLRP3 inflammasome has recently been discovered as a major driver of inflammation, thus accelerating aging and atherosclerosis." (PMID 34094640, 2021). "Melatonin has been demonstrated to ameliorate atherosclerosis by inhibiting NLRP3 inflammasome, which is regulated by SIRT3/FOXO3/Parkin signaling." (PMID 35004893, 2021). "In atherosclerosis, cholesterol crystals activate NLRP3 in macrophages inducing acute inflammation, and inhibition of NLRP3 ameliorates atherosclerosis progression." (PMID 34685542, 2021). "PepE treatment inhibited atherosclerosis development by suppressing NLRP3 inflammatory pathway in HFD-fed ApoE−/− mice." (PMID 34299310, 2021). "NLRP3 inflammasome is the key player of cytokine storm involved in cancerogenesis, heart failure and atherosclerosis." (PMID 34178667, 2021). "Recently, there have been studies investigating the role of inflammasome in cigarette smoke-induced atherosclerosis, and these studies mainly focused on NLRP3 inflammasome." (PMID 34367189, 2021). "The presence of CCs and elevated LDL are the main stimulators involved in the pathogenesis of atherosclerosis, which leads to NLRP3 inflammasome activation." (PMID 32378144, 2021). "Melatonin has also been shown to hinder the progression of atherosclerosis by mediating NLRP3 inflammasome activation and SIRT3 activity." (PMID 34292876, 2021). "In atherosclerosis, NLRP3 activation has been correlated with mitochondrial impairment by in vitro experiments showing the involvement of lectin-type oxidized LDL receptor 1 (LOX-1), a major receptor for oxLDL, in promoting mitochondrial damage." (PMID 33807807, 2021). "Treatment with NAC in HHcy mice suppressed NLRP3 inflammasome activation and improved HHcy-induced atherosclerosis." (PMID 34299310, 2021). "In the context of atherosclerosis and CCs and ox-LDL act as ‘danger signals’ and cause a reduction in the NLRP3 inflammasome in the presence of statins, while metabolic and diabetic disorders cause an activation of the NLRP3 inflammasome." (PMID 32378144, 2021). "Existing research results suggest that, similar to ECs, ROS/NF-κB/NLRP3 axis and mitochondrial damage are critical for macrophages pyroptosis in atherosclerosis." (PMID 34122076, 2021). "Although mitochondria are highly related to many inflammatory pathways, in this review, we will focus on NLRP3 activation, since it has proven to be a key event in the inflammatory process of atherosclerosis and its relationship with mitochondria." (PMID 33807807, 2021). "The contribution of the NLRP3-inflammasome to the process of atherosclerosis and its putative role as a therapeutic target is widely accepted." (PMID 34572082, 2021). "Nucleotide-binding oligomerization domain-like receptor family pyrin domain containing 3 (NLRP3) inflammasome is involved in vascular diseases including atherosclerosis." (PMID 34209567, 2021). "Recent studies have shown that the NLRP3-mediated canonical pathway is the main mechanism of ECs pyroptosis in the initiation of atherosclerosis." (PMID 34122076, 2021). "Nicotine-induced atherosclerosis via ROS/NLRP3-mediated endothelial cell pyroptosis is also prevented by NAC and VX-765." (PMID 33663554, 2021). "New therapeutic targets focusing on mitochondrial network healthiness, such as antioxidants and direct inhibition of NLRP3, are promising therapeutic approaches in atherosclerosis." (PMID 33807807, 2021). "Early-stage atherosclerosis was reportedly reduced in an NLRP3 knockout mouse fed a high cholesterol diet, indicating a close link between activation of NLRP3 and atherosclerosis progression." (PMID 33923537, 2021). "NLRP3 inflammasome-triggered inflammatory cascade has been connected to atherosclerosis, while inhibition of inflammasome enhanced atherosclerotic lesion stability." (PMID 33934111, 2021).
atherosclerosis (continued). "NLRP3 inflammasome activation is an important pathophysiological mechanism in the occurrence and development of atherosclerosis, and it has been shown that nicotine accelerated atherosclerosis mainly through NLRP3 inflammasome activation." (PMID 34490270, 2021). "Since macrophages and foam cells within atherosclerotic plaques predominantly express NLRP3 inflammasome components, the role of NLRP3 inflammasome activation in the pathogenesis of atherosclerosis has been the primary focus." (PMID 32378144, 2021). "We confirmed that nicotine triggered NLRP3 inflammasome activation and induced macrophage migration into atherosclerotic plaque, thus accelerated atherosclerosis in apoE–/– mice fed with a high-fat diet." (PMID 34490270, 2021). "As then, the mechanism of NLRP3 inflammasome involvement in atherosclerosis has been extensively studied in immune cells, including monocytes and macrophages." (PMID 33783966, 2021). "Integration of existing studies, it is proved that NLRP3-dependent macrophages and foam cell pyroptosis contributes to the progression of atherosclerosis." (PMID 34122076, 2021). "Experimental models of these diseases have proven that the NLRP3 inflammasome and its products have a central role in the pathogenesis of heart diseases as well as atherosclerosis." (PMID 33673188, 2021). "The NLRP3 inflammasome has been reported as a central regulator of inflammation during the pathogenesis of atherosclerosis." (PMID 34094640, 2021). "For example, caspase-11-gasdermin D-mediated pyroptosis and the subsequent pro-inflammatory response in macrophages are involved in the pathogenesis of atherosclerosis, and the selective NLRP3 inhibitor MCC950 hinders atherosclerosis development." (PMID 35008798, 2021). "NLRP3 is an important mechanism that drives inflammation in atherosclerosis since activation of this pathway in arterial walls by lipoproteins triggers inflammatory response." (PMID 34885795, 2021). "The NLRP3 inflammasome plays a critical role in the development of vascular inflammation and atherosclerosis." (PMID 31993073, 2020). "Some studies have shown that plaque stability was increased and the development of atherosclerosis was inhibited after NLRP3 expression was silenced by the NLRP3 shRNA virus." (PMID 32328119, 2020). "Then, ox-HDL provokes the inflammation by activating the NLRP3 inflammasome, which has a significant function in the progression of atherosclerosis." (PMID 32664349, 2020). "Enhanced autophagy can inhibit the development of atherosclerosis, and recent studies have revealed that NLRP3 inflammasome can be degraded by autophagy in atherosclerosis." (PMID 32003754, 2020). "Recent studies have indicated that the NOD-like receptor family pyrin domain containing 3 (NLRP3) inflammasome mediated inflammation plays a key role in the progression of atherosclerosis." (PMID 33442380, 2020). "The present study is the first evidence that fucoidan inhibits NLRP3 inflammasome activation by enhancing p62/SQSTM1-dependent selective autophagy to alleviate atherosclerosis." (PMID 33505579, 2020). "Through the MEG3/miR-223/NLRP3 axis, it can prevent apoptosis of endothelial cells in atherosclerosis." (PMID 32328119, 2020). "In the inflammatory process of atherosclerosis, the role of NLRP3 in the atherosclerosis has gradually got the attention of researchers." (PMID 32328119, 2020). "The severity of atherosclerosis correlates with inflammasome activity and NLRP3/caspase 1-mediated generation of IL-1β and IL-1α in human atherosclerotic plaque." (PMID 33172487, 2020). "Current studies have shown that melatonin prevented the progression of atherosclerosis by inducing mitophagy and attenuating the activation of the NLRP3 inflammasome via the Sirt3/FOXO3a/Parkin signaling pathway." (PMID 32328119, 2020). "In atherosclerosis, the NLRP3 inflammasome drives IL-1β release, thus contributing to the progression of atherosclerosis." (PMID 32148650, 2020).